LRIT2 (leucine rich repeat, Ig-like and transmembrane domains 2)
Synonyms: LRRC22; AC022389.4
Tractability: Small molecule: it belongs to a druggable protein family. Antibody: UniProt predicts a signal peptide or a membrane-spanning region.
Gene: Protein-coding gene on chromosome 10 (84,220,571 to 84,225,544, reverse strand). Ensembl gene ENSG00000204033.
Subcellular location: Membrane
Gene Ontology:
Cellular component: membrane
Genetic constraint (gnomAD): Loss-of-function variants: 23 observed, 23.63 expected, observed/expected ratio (o/e) 0.97, 90% interval 0.7 to 1.38. The upper end of that interval is the gene's LOEUF score, 1.38, which puts it in group 5 of 6, group 1 being the genes least tolerant of losing a copy. Missense variants: 753 observed, 670.36 expected, observed/expected ratio (o/e) 1.12, 90% interval 1.06 to 1.19. Synonymous variants: 283 observed, 270.41 expected, observed/expected ratio (o/e) 1.05, 90% interval 0.95 to 1.15.
Homologues: Orthologues: chimpanzee LRIT2 (99% identical), macaque LRIT2 (95% identical), rabbit LRIT2 (79% identical), pig LRIT2 (79% identical), dog LRIT2 (73% identical), mouse Lrit2 (71% identical), rat Lrit2 (71% identical), guinea pig LRIT2 (64% identical), tropical clawed frog lrit2 (42% identical), zebrafish lrit2 (41% identical). Paralogues in human: TLR8 (17% identical), NRROS (16% identical), TLR7 (16% identical), IGFALS (15% identical), TLR3 (15% identical), TLR4 (15% identical), LRRC32 (15% identical), RXFP1 (14% identical), TLR5 (14% identical), VASN (14% identical), TLR10 (14% identical), CD180 (14% identical), and 10 more.